PANX1 (pannexin 1)
Diseases named in the same sentence as PANX1 in open-access papers (continued):
Sharing a sentence is not in itself a finding about the gene and the disease.
melanoma (continued). "This localization profile in melanoma cells is different from the predominant cell surface localization observed by immunostaining with the same antibodies when PANX1 is exogenously expressed in normal reference cells." (PMID 30654593, 2019). "Taken together, this sampling of human melanoma biopsies and patient-derived primary cells indicates that PANX1 is present at high levels in melanoma tumors and cells, and at all stages of melanoma progression." (PMID 30654593, 2019). "PANX1 was localized mostly intracellularly, but we also found evidence of labeling at the cell surface of primary melanoma cells." (PMID 30654593, 2019). "In the current study, we identified high levels of endogenous PANX1 protein in human melanoma cell lines, patient biopsies and patient-derived melanoma cells from primary, nodal and distant tumors." (PMID 30654593, 2019). "We previously reported that Panx1 expression was significantly up-regulated in B16-BL6 mouse melanoma cells compared to normal melanocytes." (PMID 30654593, 2019). "Here, we assessed the effect of shRNA knockdown of PANX1 on the cellular properties of two human melanoma cell lines that express endogenous PANX1 and have different aggressiveness profiles." (PMID 30654593, 2019). "Overall our results indicate a significant role for PANX1 in regulation of growth and migration of human melanoma cells." (PMID 30654593, 2019). "This was also true from established human melanoma cell lines that displayed high endogenous PANX1 levels, and similar to what was observed in the mouse B16 lines, the levels of expression were proportional to the aggressiveness of the line." (PMID 30654593, 2019). "Our data show that reduced PANX1 level in A375-P cells results in a significant two-fold decrease in proliferation of melanoma cells after four days in culture." (PMID 30654593, 2019). "Blocking PANX1 channels with PBN reduced ATP release in A375-P cells, suggesting a potential role for PANX1 in purinergic signaling of melanoma cells." (PMID 30654593, 2019). "In this study, we show that PANX1 is highly expressed in human melanoma tumors at all stages of disease progression, as well as in patient-derived cells and established melanoma cell lines." (PMID 30654593, 2019). "To complement our studies with primary tumor samples, we also isolated and obtained populations of MITF-positive primary melanoma cells from fresh patient-derived tumors and confirmed that they exhibited high levels of endogenous PANX1 protein." (PMID 30654593, 2019). "This is consistent with our previous studies in mouse melanomas where Panx1 was found to be highly expressed in metastatic mouse melanoma cells compared to basal levels found in normal melanocytes." (PMID 30654593, 2019). "Inhibiting PANX1 channels increases melanin production, and affects signaling pathways that regulate melanoma progression, identifying PANX1 as a potential therapeutic target for melanoma treatment." (PMID 30654593, 2019). "Immunofluorescence analysis revealed PANX1 is localized intracellularly and at the cell surface of both human melanoma cell lines, comparable to our patient-derived primary cells, with apparent punctate staining in some cells." (PMID 30654593, 2019). "Previously, we have shown that the malignant properties of a mouse melanoma cell line were reduced following shRNA-induced silencing of Panx1." (PMID 30654593, 2019). "Taken together, these results suggest a reduction in growth and migration of human melanoma cells, with an increase in melanin production in the presence of PANX1 channels inhibitors." (PMID 30654593, 2019). "Collectively, our findings identify a role for PANX1 in controlling growth and tumorigenic properties of melanoma cells contributing to signaling pathways that modulate melanoma progression." (PMID 30654593, 2019). "Using our previously characterized antibodies, PANX1 was readily detected in primary melanoma tumors, nodal and distant metastases obtained from banked specimens." (PMID 30654593, 2019).
melanoma (continued). "Given the limited nature and shorter lifespan of primary cells from patients, we set out to evaluate the endogenous PANX1 expression in a panel of established human melanoma cell lines that differ in origin and metastatic profiles." (PMID 30654593, 2019). "Cells were derived from fresh primary, nodal and distant melanoma tumors to evaluate PANX1 levels and localization in the melanoma cells from each tumor." (PMID 30654593, 2019). "Regarding the potential function of the intracellular pool, we have previously shown that shRNA-mediated Panx1 knockdown decreases β-catenin levels in a mouse melanoma cell line B16-BL6." (PMID 30654593, 2019). "Melanin production (a marker of melanocytic differentiation,) was increased with all the treatments, indicating a potential effect of PANX1 channel function on the cell signaling of melanoma cells as we had previously reported for mouse melanomas." (PMID 30654593, 2019). "We concluded that human melanomas express high levels of PANX1 that when targeted via chemical blockers or genetic silencing reduce melanoma growth, migratory capacity, tumorigenesis and invasiveness." (PMID 30654593, 2019). "Our results show high endogenous PANX1 levels in primary cells derived from three different stages of melanoma progression compared between patients, or among stages of progression in the same patient." (PMID 30654593, 2019). "The data showed that PANX1 expression in primary melanoma tumors is significantly increased relative to normal skin biopsies." (PMID 30654593, 2019). "In contrast with other studies that have reported marked differences in the expression of Panx1 between rat and human cancer cell lines, we found that human melanoma cells and biopsies were all positive for PANX1 regardless of the disease stage." (PMID 30654593, 2019). "Our published data indicate that knocking down Panx1 in aggressive BL6 melanoma cells results in a substantial reduction of β-catenin abundance, and decreased proliferation." (PMID 30385873, 2018). "In melanomas, P2X7/PANX1 channel activity has been linked to regulation of the NLRP3 inflammasome, which can result in release of pro-inflammatory, tumour promoting cytokines." (PMID 29865195, 2018). "Knockdown of Panx1 in tumour cells decreases tumour cell growth, which indicates Panx1 as a potential target for treating melanoma." (PMID 29865195, 2018). "It was then reported that Panx1 levels are up-regulated in murine melanoma cell lines and correlated with their aggressiveness." (PMID 30459312, 2018). "Panx1 is present in skin melanocytes and is upregulated during melanoma tumour progression and tumorigenesis." (PMID 29865195, 2018). "Recently, two articles have highlighted the link between inflammation and melanoma, proposing the involvement of the Panx1/P2X7 complex as a key regulator." (PMID 27229305, 2016). "At the protein level, Panx1 expression is listed in 17 out of 20 tumour types (high in colorectal, lung, urothelial and stomach cancers), and up to 70 % of human melanoma tumours show high levels of Panx1 protein (Human Protein Atlas)." (PMID 27229305, 2016). "In a chick-chorioallantoic membrane assay (chick-CAM), the mouse melanoma tumors with Panx1 shRNA were significantly smaller and had less instances of metastasis to the liver than the aggressive wild-type cells with high Panx1." (PMID 27229305, 2016). "We proposed Panx1 as an interesting new target for therapeutic intervention in the fight against melanoma." (PMID 27229305, 2016). "Panx1 is crucial for tumor cell proliferation, including melanoma, cSCC, and pancreatic cancer." (PMID 40909173, 2025). "Furthermore, studies in melanoma cells have identified that Panx1 deletion increases T lymphocyte infiltration within the tumor microenvironment, suggesting a dual role in tumor and immune regulation." (PMID 40978734, 2025).
melanoma (continued). "This suggests PANX1 action through its signalling and interactome also contributes to cancer cell properties, similar to the interplay between PANX1 and the canonical Wnt pathway in melanoma." (PMID 39560179, 2025). "Since shRNA knockdown of Panx1 was reported to reduce mRNA levels of β-catenin in human melanoma cells, we further explored whether the Wnt/β-catenin signaling was involved in Panx1 KO DRGNs." (PMID 38685116, 2024). "Taken together, these results indicated that Panx1 deficiency did not impair the overall recruitment of immune cells to the primary tumors in this melanoma model but had an effect on increasing the transcript expression of CD8 in skin and tumors of BPC mice." (PMID 38327091, 2024). "Thus, PANX1 plays an important role in WNT signaling for both melanoma cells and neuroepithelial cells, albeit through different mechanisms." (PMID 38212304, 2024). "A possible solution to this problem could include the use of a syngeneic mouse model where Panx1 deletion can be targeted to specific immune cell types and be studied in a more relevant immunogenic melanoma model like YOVAL1.1." (PMID 38327091, 2024). "Moreover, our studies show that in Panx1 wildtype mice, normal melanocytes express low levels of PANX1 which are upregulated in melanoma cells." (PMID 38327091, 2024). "It is known that sexual dimorphism exists in the response of Panx1‐deficient mice in ischemia and epilepsy, and research on this is still lacking in the melanoma and immune cell recruitment contexts." (PMID 38327091, 2024). "Since this is a highly penetrant mouse model, a syngeneic melanoma model may be more suitable to study the effect of Panx1 deletion in melanoma metastasis." (PMID 38327091, 2024). "We anticipate that targeting PANX1 in melanoma may increase the homing of effector T lymphocytes to melanoma tumors which in the future could be harnessed to improve the effect of immunotherapies." (PMID 38327091, 2024). "Furthermore, we have shown promising results after silencing Panx1 expression and reducing the growth and tumorigenicity of melanoma cell lines in vitro." (PMID 38327091, 2024). "All these findings place PANX1 as an attractive target for preclinical melanoma research, but it is still unclear whether the silencing of this gene would impact melanoma development in vivo." (PMID 38327091, 2024). "In non-melanoma human skin cancers, the downregulation of Panx1 may indicate its protective function against keratinocyte transformation." (PMID 36833374, 2023). "Recent studies have suggested that PANX1 may have a wide range of biological effects on cancer development, including the promotion of cell proliferation and tumorigenesis in melanoma, brain tumors, and hepatocellular carcinoma." (PMID 36291937, 2022). "Given the similarity of connexin and pannexin structure, we investigated whether calmodulin interacts with PANX1 in melanoma cells." (PMID 33647315, 2021). "Our data revealed that reducing PANX1 in melanoma cells suppresses their mitochondrial metabolism." (PMID 33647315, 2021). "In addition, the pattern of β-catenin staining at cell borders is also irregular and disrupted when PANX1 is reduced in melanoma cells." (PMID 33647315, 2021). "Endogenous PANX1 co-immunoprecipitated (co-IP) with β-catenin in 131/4-5B1 human melanoma cells." (PMID 33647315, 2021). "LEF1 mRNA was significantly reduced when we knocked down PANX1 in A375-P melanoma cells." (PMID 33647315, 2021). "Additionally, two specific PANX1 blockers tested in our study significantly reduce the abundance of both PANX1 and β-catenin proteins in melanoma cells." (PMID 33647315, 2021). "Our findings underline the molecular mechanisms through which PANX1 regulates melanoma tumorigenesis and suggests that PANX1 may be a new interactor in the Wnt signaling pathway and can potentially be a target for the treatment of malignant melanoma." (PMID 33647315, 2021).
melanoma (continued). "We hypothesized that reduction of PANX1 and consequently β-catenin would alter the metabolic profile of melanoma cells." (PMID 33647315, 2021). "We also observed increased PANX1 abundance in A375-MA2 compared to A375-P melanoma cells." (PMID 30654593, 2019). "Although PANX1 has been shown to have a predominantly cell surface localization when exogenously expressed, we noticed a marked intracellular signal from PANX1 protein in immunofluorescence microscopy images of both patient-derived primary melanoma cells and established human melanoma cell lines." (PMID 30654593, 2019). "However, it is clear that PANX1 and β-catenin are intimately connected since shRNA of pannexin 1 in either mouse or human melanoma cells leads to a marked reduction in β-catenin levels." (PMID 30654593, 2019). "To investigate whether PANX1 plays a role in the context of human melanoma, we first evaluated gene expression analyses in a microarray study." (PMID 30654593, 2019). "It is possible that PANX1-associated ATP may act in conjunction with purinergic receptors like P2X7, to enhance melanoma growth." (PMID 30654593, 2019). "For example, the reduction in PANX1 may destabilize the Wnt/β-catenin complex and alter this important signaling pathway in melanoma." (PMID 30654593, 2019). "Next, we examined if PANX1 protein was present in melanoma biopsies." (PMID 30654593, 2019). "In addition, cell-surface biotinylation assays indicate that there is an intracellular pool of PANX1 in melanoma cells." (PMID 30654593, 2019). "However, the situation is not so clear and probably depends on the cell type by considering melanocytes in which Panx1 expression is low whereas increased expression is correlated with melanoma aggressiveness." (PMID 29865195, 2018). "The apparent discordances between the effects of Panx1 expression in proliferation and motility of melanoma, glioma and epithelial tumor cells could be due to tumor cell-specific and/or cell lineage-specific functions of hemichannels." (PMID 25018732, 2014). "In this model, down regulation of Panx1 using siRNAs significantly reduced the expression of the malignant melanoma markers vimentin, hsp70 and B-catenin, and diminished the cell density and motility, but increased melanin production suggesting acquisition of a more differentiated phenotype." (PMID 25018732, 2014). "In human A375‐P and A375‐MA2 melanoma cells, decreased cellular growth rate, migration, invasion and mitochondrial metabolic activity, as well as increased melanin production, were observed when PANX1 channel activity was inhibited or PANX1 levels were reduced via shRNA knockdown." (PMID 39560179, 2025). "Our group showed PANX1 levels are increased in melanoma cells compared to normal melanocytes, and PANX1 mRNA is upregulated in patient melanoma tumour samples compared to control skin, with levels remaining high throughout all stages of melanoma disease progression." (PMID 39560179, 2025). "Notably, β-catenin levels were found to be lower in periosteal bone from Panx1 KO mice compared to WT, indicating that mechanoresponsive Wnt signaling was impaired in Panx1-null osteocytes, and β-catenin expression declined when Panx1 was knocked down in melanoma cells." (PMID 38685116, 2024). "Moreover, depletion of PANX1 attenuated the mitochondrial respiratory activity of melanoma cells." (PMID 33647315, 2021). "Thus, we postulated that reducing PANX1 might similarly affect the Wnt/β-catenin pathway in human melanoma cells." (PMID 30654593, 2019). "From our results, we conclude that PANX1 plays an important role in the regulation and progression of melanoma and may be a novel therapeutic target at all stages of melanoma progression, thus potentially improving current treatment options for individuals with melanoma." (PMID 30654593, 2019).
melanoma (continued). "We have demonstrated that PANX1 influences the regulation of effector molecules that control melanocyte differentiation (e.g., MITF and β‐catenin) and the metabolism of melanoma cells." (PMID 38327091, 2024). "However, our recent findings indicate that knocking down (KD) PANX1 with shRNA in aggressive BL6 mouse melanoma cells, as well as in human melanoma cell lines, reduces the abundance of β-catenin, a key transcription factor in the Wnt signaling pathway implicated in melanoma tumorigenesis." (PMID 33647315, 2021). "Previous studies showed that PANX1 was overexpressed in hepatocellular carcinoma (HCC), gastric cancer cells, and melanoma cells." (PMID 34796785, 2021). "Freeman and colleagues showed that reducing Panx1 protein levels with shRNA, or blockade of Panx1 channel activity using carbenoxolone or probenecid, significantly reduced the level of cell growth and cell migration of A375-P and A375-MA2 melanoma cell lines." (PMID 34068881, 2021). "Using scrambled shRNA as a control, we confirmed a significant PANX1 knockdown in A375-P and A375-MA2 melanoma cells by immunoblotting." (PMID 30654593, 2019). "Immunoblot analysis of lysates from melanoma cells transfected with scrambled shRNA (SCR shRNA) showed comparable endogenous levels of both β-catenin and PANX1 to un-transfected A375-P and A375-MA2 cells." (PMID 30654593, 2019). "However, as evidenced by the cell-surface biotinylation results, a subpopulation of endogenous PANX1 in these melanoma cells is localized intracellularly and may be playing a different role, unrelated to their canonical cell surface ATP release channel function." (PMID 30654593, 2019). "PANX1 knock down reverted BL6 cells to a more normal melanocyte phenotype and these cells had reduced levels of vimentin and β-catenin, both markers of melanoma progression." (PMID 29865195, 2018). "In conclusion, Panx1/P2X7 is upstream of the NLRP3 inflammasome, but two different arms of its downstream signalling pathway could be either implicated in tumorigenesis in the case of melanomas, or cell death in the case of colon cancer cells that express LXRs." (PMID 27229305, 2016). "In some cases, the knockdown of Panx1 can revert the cancer cells to a more normal phenotype, as we reported for B16-BL6 mouse melanoma cells, described in detail below." (PMID 27229305, 2016). "In vitro melanoma models and transgenic BRAF/Pten mouse models demonstrated that Panx1 deletion increases T lymphocyte infiltration within the tumor microenvironment, although it does not significantly affect primary tumor formation, suggesting a dual role in tumor and immune regulation." (PMID 40978734, 2025). "Since our previous reports indicated that PANX1 is highly expressed in human melanoma tumors compared to normal skin, we performed real‐time qPCR in matched samples of non‐tamoxifen‐treated (adjacent) skin and tamoxifen‐induced tumors." (PMID 38327091, 2024). "In this work, using the immunocompetent BPC mouse melanoma model, we did not observe a reduction in Braf(V600E)/Pten(del)‐driven melanomas or improve mice survival upon germline Panx1 deletion." (PMID 38327091, 2024). "Although the PANX1 channel protein is highly expressed in melanoma, we found that global deletion of Panx1 did not prevent tumor onset, progression, or lymph node invasion in a mouse model of melanoma (Braf/Pten; BPC)." (PMID 38327091, 2024). "Our results suggest that, although Panx1 deletion does not overturn the aggressive BRAF/Pten‐driven melanoma progression in vivo, it does increase the infiltration of effector immune T‐cell populations in the tumor microenvironment." (PMID 38327091, 2024). "Regional black melanoma metastases were found in both right and left inguinal lymph nodes in both Panx1 genotypes but this was not noticeable in major organs (e.g., lungs, liver, or brain)." (PMID 38327091, 2024).